CD4 (CD4 molecule)
Diseases named in the same sentence as CD4 in open-access papers (continued):
Sharing a sentence is not in itself a finding about the gene and the disease.
infection (continued). "We recently described a unique SIV model in which such CD4-independent Env variants emerged and dominated in the plasma of multiple rhesus macaques experimentally depleted of peripheral (but not mucosal) CD4+ T cells prior to infection." (PMID 24219995, 2013). "Consequently, suboptimal stimulation of the target CD4+ T cell through the virological synapse may be all that is required for productive infection of an otherwise resistant T cell." (PMID 23772628, 2013). "The low numbers of CD137+ CD4+ cells are probably sufficient to maintain myelopoiesis during aging, while a fast expansion of CD137+ CD4+ T cells may only be required during emergencies, such as infections, when a more substantial increase in myelopoiesis is needed for pathogen clearance." (PMID 23945137, 2013). "Likewise, Vitelli-Avelar reported decreased levels of CD62L+CD4+ T cells but lower frequencies of CD4+HLA-DR+ T cells along with unaltered levels of CD4+CD28+ T cells in children in the indeterminate phase of the infection." (PMID 24349591, 2013). "Thus, the vaccine-induced response generated by TB10.4 was very similar to the ESAT-6 induced response both in terms of magnitude and quality i.e. the proportion of IFN-γ+IL-2+TNF-α+ CD4 T cells and differed markedly from the infection promoted response to these antigens." (PMID 24349004, 2013). "Rather, direct infection of long-lived resting IL-7R+ CD4 T-cells, while they transit through infected lymphoid tissue, may be more likely to result in the cART-resistant reservoir, and that IL-7 maintains homeostasis of these memory CD4 T-cells." (PMID 23630526, 2013). "However, this latter data needs to be interpreted in light of the marked depletion of CD4+ T cells in gut post infection and the presence of detectable levels of PD-1hi CD4+ cells in the lamina propria of this tissue, especially at the chronic stage of infection (ongoing investigations)." (PMID 23555918, 2013). "Thus, following infection with a particular pathogen, Bim can promote CD4+ T cell survival during the transition to memory, but the development of memory function is Bim-independent, as evidenced by the survival of Bim-deficient SMARTA memory cells that were profoundly dysfunctional." (PMID 23840678, 2013). "Following infection with L. major, the T cell-specific and complete IL-10-deficient mice on the C57BL/6 as well as the BALB/c background are characterized by an increased early inflammation, which is due to the enhanced secretion of IFN-γ by CD4+ as well as CD8+ T cells." (PMID 23825956, 2013). "Hence, there might be a pathway of direct infection of resting T cells also in vivo during normal chemokine-directed recirculation of CD4+ T cells between blood and tissue." (PMID 23803414, 2013). "However, different routes and mechanisms of infection of CD4+ T cells may contribute to the establishment of HIV reservoirs and increased HIV pathogenesis." (PMID 24244453, 2013). "Absence of CD4+ T-cells restored susceptibility to infection in Itgb8 (CD11c-Cre) mice." (PMID 24098124, 2013). "• An increased percentage of BTLA+CD4+ T cells in critically ill patients associated with poor outcomes and a longer hospital length of stay; thus, future studies are warranted examining BTLA expression on CD4+ T cells as a potential biomarker for subsequent infections and poor septic outcomes." (PMID 24289156, 2013). "It was recently reported that the direct infection of resting CD4+ T cells by spinoculation results in the generation of a population of cells carrying integrated proviruses, that are capable of producing low levels of Gag but are unable to spread the infection." (PMID 23803414, 2013). "The idea that Treg cell inactivation contributes to the early CD4+ T cell response to infection is indirectly supported by our data showing a massive response to parasites in non-infected mice a month after JES6-1 treatment, a condition where Treg cells may have been inactivated by IL-2 deprivation." (PMID 22272258, 2012).
infection (continued). "One study has shown that CD4+ cells from controllers are less susceptible to HIV compared to CD4+ cells from progressors and healthy controls, while another study showed that CD4+ cells from controllers were as susceptible or even more susceptible to HIV entry and productive infection." (PMID 22693657, 2012). "As such, the association between lack of detectable viral replication on day 9 post-inoculation and reduced baseline frequencies of CD4+ CD69+ T cells supports the hypothesis that T cell immune quiescence can limit infection by reducing the pool of activated HIV target cells." (PMID 23029309, 2012). "However, it remained unknown whether virus-specific T cell responses would be elicited in humanized mice after infection with HIV-1 targeting human CD4+ T cells." (PMID 22880104, 2012). "Enhanced infection of primary macrophages was seen in the RP macaques at end-stage disease irrespective of coreceptor switch, indicative of a strong selective pressure to replicate in cells with lower CD4 cell-surface expression levels over the infection course." (PMID 23237529, 2012). "More direct comparisons between in vitro infections of PBMCs and T cell lines have also shown considerable disparities between these cell types, emphasizing a need for conducting future studies in primary cells whenever possible, particularly purified CD4+ T cells and macrophages." (PMID 23170164, 2012). "Infected CD4+ T lymphocytes (without immune clearance) can produce up to a maximum of about 20,000 virions (most of which are nonviable), resulting in a basic reproductive rate of each infected cell causing the infection of 10 new cells." (PMID 23028619, 2012). "As we have previously shown that resting CD4+T cells are susceptible to HIV integration, we asked whether these cells were capable of producing viral proteins and if so, why resting cells were incapable of supporting productive infection." (PMID 22911005, 2012). "However, productive infection rates in primary human cells such as CD4+ T lymphocytes are very low." (PMID 22876188, 2012). "Consequently, CD4+CCR6+ cell numbers started to rise from d 6 of infection in the lymph node." (PMID 23028548, 2012). "Thus, we can assume that in settings (like Cotonou) where, during the study period, ART was initiated in patients with advanced infection (CD4<200/mm3 or WHO clinical stage 3 with CD4<350/mm3 or WHO stage 4 regardless of CD4 cell count), older people were more likely to be treated." (PMID 22952773, 2012). "Interestingly, we observed that HERV-K expression, at least at the level of transcription, was inversely associated with immune activation but not with standard clinical measures of HIV-1 disease status (CD4+ T cell blood count and plasma viral load) in patients with progressive infection." (PMID 22879884, 2012). "Besides producing IFN-γ, direct killing activity of CD4+ T cells, which has been described in lymphocytic choriomeningitis virus, West Nile virus and dengue virus infection, might also be a function of these cells." (PMID 22912884, 2012). "Despite the reduced CD4 cell count, the haematologic and clinical response to purine analogues increases macrophage cell activity and often also hypogammaglobulinemia; for this reason infections are more frequent at the beginning of the disease and decrease with improvement of CLL." (PMID 23205258, 2012). "Although not necessary for HIV-1 entry into CD4+ T cells, Env lacking specific glycosites within the V1 and V2 loops of gp120 have greater access to bind α4β7, an interaction that has been shown to promote a greater susceptibility to infection." (PMID 22731404, 2012). "In addition, it was recently reported that during mouse footpad infections with virulent M. ulcerans, pathogen-specific gamma interferon (IFN-γ)-producing T cells develop early in the draining lymph node (DLN) and that CD4+ T cells migrate to the infection foci." (PMID 22393444, 2012).
infection (continued). "In vivo experiments using a humanized mouse model of HIV infection also showed that CCR5-modified CD4 T cells engrafted into the animals at levels similar to unmodified CD4 cells, and are capable of controlling viral load and maintaining CD4 counts following infection with R5-tropic viruses." (PMID 22470838, 2012). "Besides displaying variation in magnitude, the kinetics of Salmonella-specific CD4+ T cell responses were also diverse: whereas STM1540262–276-specific CD4+ T cell responses increase until day 21, the responses against the AhpC154–168 and FliC429–443 epitopes contracted after day 14 post-infection." (PMID 22912884, 2012). "However, basophils may play a major role in type-2-mediated secondary infection in conjunction with CD4+ T cells, as depletion of IL-4 and IL-13 in both basophils and CD4+ T cells was necessary to abrogate protection." (PMID 22360486, 2012). "Despite sampling multiple independent gastric mucosal sites to arrive at this conclusion, the apparent persistence of gastric mucosal CD4+IL-17A+ cells in patients from group P might still be due to ongoing infection with HP at localised sites that were missed during endoscopy." (PMID 22761739, 2012). "However, the number of CD4+ T cells is increased in cervicovaginal secretions with certain infections; this is consistent with the observation that detection of HTLV-1-infected cells in cervical secretions was associated with inflammation of the uterine cervix." (PMID 23109932, 2012). "Indeed, myeloid DCs can contribute to the spread of HIV-1 through trans-infection of CD4+ T cells." (PMID 23271952, 2012). "Thus, naïve Salmonella-specific CD4 T cells will encounter flagellin only during the early stage of infection within the intestine, whereas SPI-2 TTSS effector proteins accumulate as more intracellular bacteria replicate in the systemic tissues of the spleen and liver." (PMID 22275869, 2012). "The proportion of CD4+ T cells was significantly decreased after yellow cattle were challenged with schistosomes, and was significantly decreased at 2w post infection, increased slightly at 4w post infection, then decreased again at 7w post infection in yellow cattle." (PMID 22414188, 2012). "To examine what pathways might be involved, we focused on CD4 T cells and found significantly elevated levels of the pro-apoptotic Fas-receptor on days 5, 8 and 20 post infection on OX40-deficient cells suggestive of negative regulation of Fas by OX40." (PMID 22969431, 2012). "However, a recent study demonstrated that the pro-inflammatory cytokines, TNFα, IFNγ and IL-2, were produced by T cells (CD8+ and CD4+) at higher levels in individuals who subsequently developed subclinical secondary DENV infections versus symptomatic infections." (PMID 22816004, 2012). "Lastly, FV-neutralizing antibodies were similarly and efficiently induced in T cell-deficient Tcra−/− hosts by transfer of either type of donor CD4+ T cells, although they were slightly, but not significantly higher in hosts of Emv2-nonselected CD4+ T cells on day 7 post infection." (PMID 22589728, 2012). "Studies on different subpopulations of T cells have brought further insight into the importance of T cells during T. muris infection, showing that depletion of CD4+ T cells but not CD8+ T cells or NK1.1+ natural killer T cells with neutralizing antibodies resulted in susceptibility to infection." (PMID 23053395, 2012). "Future experiments with soluble PTX, such as antigen pulsing experiments, are required to further address whether the imprinting defect is related to the antigen presented or due to a direct effect on the lung DCs ability to effectively interact with CD4+ cells in this infection." (PMID 23300813, 2012).
infection (continued). "Importantly, and in support of our earlier findings, the increase in sCD4 sensitivity of the evolving R5 viruses in DE86 and DG08 was accompanied by a corresponding increase in the binding of the gp120s to CD4-Ig and in infection of primary macrophages that express low amounts of the CD4 receptor." (PMID 23237529, 2012). "CD4+ T cell specific (LckcreIL-4Rα−/lox) IL-4Rα−/− mice are more resistant than global IL-4Rα−/− mice to infection with L. major, indicating that in the absence of a polarized Th2 response, there is a role for an IL-4/IL-13 responsive non-CD4+ T cell in early resistance to infection." (PMID 21245915, 2011). "However, infection status did not alter the in vitro suppressive ability on a per-cell basis of CD4+CD25+Tregs from the mLN, indicating that infection-expanded CD4+FoxP3+Tregs and those from naïve mice share a common mechanism of Th2-effector cell suppression." (PMID 21858239, 2011). "The levels or cell surface density of both CD4 and HIV Co-R in these different subsets of T cells may play a significant role in the efficiency of virion-cell membrane fusion and, consequently, their susceptibility to infection." (PMID 21284907, 2011). "However, other studies have also demonstrated that infections of various T-cell lines, activated or resting primary CD4+ T-lymphocytes and macrophages, may lead to expression of a limited range of viral proteins in the absence of viral integration." (PMID 21722380, 2011). "Although treated mice still developed a productive infection with HIV-1, the mean plasma viral load was decreased about 30-fold relative to control vector-transduced mice and no CD4+ T cell loss was noted in treated mice for up to 55 days while CD4+ T cell loss was detected with the control vector." (PMID 21835012, 2011). "The capacity of thymic pDC to efficiently transfer R5 HIV-1 to both mature and immature thymocytes that are otherwise refractory to R5 virus may represent a pathway to early infection and impaired production of thymocytes and CD4+ T cells in HIV-1-infected individuals." (PMID 21639903, 2011). "Thus, a low initial CD4+ count might allow a wide dissemination of the parasite throughout the phagocytic mononuclear system at the beginning of infection, increasing the number of sites that could harbor quiescent parasites (so-called “sanctuaries”)." (PMID 21666786, 2011). "Susceptibility to infection by the human immunodeficiency virus type-1 (HIV-1), both in vitro and in vivo, requires the interaction between its envelope (Env) glycoprotein gp120 Env and the primary receptor (R), CD4, and Co-R, either CCR5 or CXCR4, members of the chemokine receptor family." (PMID 21284907, 2011). "HIV-1 variants that do not require CD4 for infection have been isolated in vitro and in vivo." (PMID 21541353, 2011). "In addition, the results also suggested it may be the egg antigens of S. japonicum that were responsible for the more rapid increase in the proportion of Th17 cells in total CD4+ T cells from five weeks onward after infection." (PMID 22102924, 2011). "Moreover, our results suggest that once infection is established, the naïve CD4+ T-cell compartment is further impaired by an accelerated loss of CD31+CD4+ naïve T-cells, and a loss of CD31- naïve T-cells that is not normally associated with SN adults in their fifties." (PMID 21298072, 2011). "Furthermore, the inability of hCD4 positive squamous cell carcinoma (SCL1) and astroglial cells (U87MG) to form syncitia with cells expressing HIV-1 envelope demonstrated that infection with the newly-discovered virus required secondary receptor(s) in addition to CD4." (PMID 21284905, 2011). "However, some mutants have an advantage as they may allow escape from immune surveillance or more effective infection of certain tissue compartments or cell types, such as cells in the brain or the genital tract or naïve CD4+ T-cells, which express CXCR4." (PMID 21829600, 2011).
infection (continued). "The mechanisms for the enhancement of in vitro infection reported for C-HIV may involve focusing the virions via complement to cholesterol rich membrane areas with increased densities of CD4 and coreceptor to facilitate infection both at the cell surface and possibly in the endosomal compartment." (PMID 21853149, 2011). "While a transient reduction in T and B cell populations is observed during the first week after infection, the CD4+ T cell population remains depleted for 30 days postinfection, which could cause dysfunction of the immune system and favour opportunistic infections." (PMID 22312347, 2011). "Multiple mechanisms have been proposed to explain infection-induced immunosuppression, including an imbalance in the cellular helper T cell (Th1/Th2) or cytokine profile, induction of anergy, depletion of effector cells and most recently the activation of CD4+CD25+ Tregs." (PMID 22069445, 2011). "Understanding of the immune response to infection has expanded greatly in recent years and, as for many aspects of immunology, this new knowledge is based on application of the discovery of multiple functional subsets of T lymphocytes expressing the CD4 co-receptor molecule." (PMID 21489234, 2011). "Moreover, HIV-1 also down-regulates autophagy in CD4+ T cells during productive infection." (PMID 21247613, 2011). "However, whereas higher expression levels of DC-SIGN enhanced binding of IIIB and IIIBx to the same extent, the actual infection of the CD4 dependent IIIB is more enhanced (p = 0.001) than that of the CD4 independent IIIBx (34-fold increase for IIIB, 8-fold increase for IIIBx)." (PMID 22163292, 2011). "Therefore, the CD4-dependent mechanism of Nef-mediated infectivity enhancement probably relies on increasing the number of functional envelope-CD4 receptor interactions and thereby the likelihood of productive infection." (PMID 22103831, 2011). "Moreover it has been hypothesized that the Tregs cell homing in sites of infection may be driven by the chemokine receptor CCR5 that is described to be preferentially expressed by Tregs compared with normal CD4+ T cells." (PMID 21559446, 2011). "Therefore, we hypothesized that one mechanismwhereby M. tuberculosis avoids elimination is by limitingactivation of CD4+ effector T cells at the site of infection inthe lungs." (PMID 21637811, 2011). "Another confounding factor might therefore be the actual contribution of Nef to CD4 downmodulation at the moment of virus collection, since CD4 downmodulation is known to occur in a Nef-independent manner during later stages of infection, by actions of both Vpu and Env." (PMID 22103831, 2011). "Consequently, it may be that the preferential mode of action found by CD8 T (in spite of a clear CD4 T cell response) is biased by the release and subcellular localization of this antigen during infection." (PMID 21695103, 2011). "Even though the vaccine-induced GagCM9-specific CD8+ T cells in our current study expanded to high frequencies by two weeks post-SIVsmE660 infection, the SIV-specific CD8+ T cell response may have simply arrived too late to control viral replication and prevent CD4+ T cell loss in the gut mucosa." (PMID 21887264, 2011). "However, the discounted QALYs lost to HIV infection were the same in both the ED and STD clinic settings because we assumed that index patients linked to care in these settings initiated HAART at the same time following infection, i.e., when their CD4 counts decreased to 350 cells/μL." (PMID 21625489, 2011). "To investigate whether the increased stability of the CD4 complex with gp140 contributes to infection with HIV, we compared the effects of cis-expression of DC-SIGN on in vitro infection with HIV-1 IIIB and HIV-1 IIIBx, a variant of IIIB that can bind directly to CXCR4 without CD4." (PMID 22163292, 2011).